EGFR (epidermal growth factor receptor)
Diseases named in the same sentence as EGFR in open-access papers (continued):
Sharing a sentence is not in itself a finding about the gene and the disease.
glioblastoma (continued). "Heterogeneity of another EGFR mutation, EGFRvII, occurring less frequently in glioblastoma than EGFRvIII mutation, similarly displayed a constant heterogeneity, as evidenced by single cell sequencing." (PMID 30279357, 2018). "In fact, EGFRvIII variant expression makes glioblastoma cells more sensitive to EGFR tyrosine kinase inhibitors." (PMID 30279357, 2018). "Epidermal growth factor receptor (EGFR) and EGFR variant (EGFRvIII) are over-expressed in many cancer types and are commonly associated with the malignancy of glioblastoma." (PMID 29568411, 2018). "Drug-resistant U87.MG ΔEGFR glioblastoma cells harboring mutated epidermal growth factor receptor were even more sensitive (collateral sensitive) than wild-type U87.MG cells (resistance ratio: 0.33)." (PMID 29535630, 2018). "The fundamental importance of this pathway is directly supported by the observation that EGFR is mutationally activated in more than 50% of glioblastomas." (PMID 30279357, 2018). "Oncogenic EGFR mutations and large genetic rearrangements (as observed in glioblastoma, brain, lung, breast, and ovarian cancers) often cause altered receptor endocytosis, which contributes to increased signaling properties." (PMID 29124875, 2018). "Chromosome 7 is usually disrupted in many cancers, here we detected the amplification of several genes already implicated in glioblastoma such as: EGFR, SEPT14, NAMPT, NRCAM, AAS and PTPRZ1." (PMID 29844869, 2018). "It is important to note that overall, 57% of glioblastoma samples showed evidence of mutation, rearrangement, altered splicing, and/or focal amplifications of EGFR." (PMID 30279357, 2018). "The first phase II trial in type III epidermal growth factor receptor mutation (EGFRvIII)-expressing glioblastoma used overall survival as an endpoint." (PMID 30454061, 2018). "The constitutively activated variant EGFRvIII is present in cells with EGFR gene amplification and is believed to increase the tumorigenic potential, particularly in glioblastoma cells." (PMID 30150691, 2018). "In primary glioblastoma, the most common genetic disorder is the loss of heterozygosity on chromosome 10q (70%), amplification of the EGFR (36%), PTEN mutations, and deletion of p16." (PMID 29805974, 2018). "Activating mutations or amplification of EGFR are observed in 45–57.4% of glioblastomas, and frequently occur in the “Classical” subgroup of glioblastomas." (PMID 30514230, 2018). "Lastly, the EGFR variant, EGFRvIII, is a tumor-specific truncated version of the EGFR receptor, making it an attractive glioblastoma cell-surface target for CAR T cells." (PMID 30568917, 2018). "In glioblastoma tumors, the common EGFR mutation is in frame deletion of exon 2–7 resulting in ligand-binding domain deletion of the EGFR." (PMID 29867487, 2018). "Amplification of the gene encoding the EGFR occurs commonly in glioblastoma (GBM), the most common malignant primary brain tumor of adults." (PMID 29455662, 2018). "OSMR forms a complex with EGFRvIII, the most common EGFR mutation that occurs in glioblastoma, and regulates glioblastoma tumour growth." (PMID 30382873, 2018). "For instance, EVs from xenografts of glioblastomas contain an oncogenic variant of the epidermal growth factor receptor (EGFRvIII), which can be transferred to endothelial cells, producing proliferation and tubulogenesis." (PMID 30279961, 2018). "In this study, we show that treatment of glioblastoma cells with 17-AAG leads to HSP90 inhibition indicated by loss of stability of the EGFR client protein, and significant increase in HSP70 expression." (PMID 28542269, 2017). "EGFR is overexpressed in 50–60% of glioblastomas and is amplified in 40% of the tumors, and half of these contain various EGFR mutations." (PMID 29152086, 2017).
glioblastoma (continued). "Gene amplification and overexpression of the EGFR protein and its mutant variant EGFRvIII contributes to glioblastoma tumorigenesis and has been the target for new therapeutics." (PMID 29189740, 2017). "Somatic mutations that lead to EGFR overactivity or upregulation are associated with several types of cancer (e.g., glioblastoma multiforme (GBM), lung cancer, or anal cancers)." (PMID 28191459, 2017). "Aberrant amplification and mutations of epidermal growth factor receptor (EGFR) are the most common oncogenic events in glioblastoma (GBM), but the mechanisms by which they promote aggressive pathogenesis are not well understood." (PMID 29129908, 2017). "There are genetic aberrations associated with GBM; amplification of epidermal growth factor receptor (EGFR) is a frequent finding that has been described in 40-50% of all human glioblastomas." (PMID 29069805, 2017). "Glioblastomas exhibit EGFR overexpression in more than 4/5 of cases and more than half of those were tested with an additional expression of the EGFR deletion variant EGFRvIII." (PMID 28445134, 2017). "We immunized mice with a combination of the extracellular domain of EGFR and EGFR-overexpressing LN229 glioblastoma cells (LN229/EGFR) and performed the first screening using enzyme-linked immunosorbent assay." (PMID 29090976, 2017). "Even though targeting aberrations that are only altered in a subset of tumour cells can cause clonal selection and drug resistance, targeting EGFR variants can indeed prolong survival in glioblastoma patients, despite tumour recurrence." (PMID 28800767, 2017). "EGFR associated mutations, amplification or overexpression are observed in approximately 50 % of glioblastoma patients." (PMID 28611289, 2017). "EGFRvIII-positive tumors have been associated with poor prognosis and shorter life expectancy and both EGFR and EGFRvIII have been linked to the invasive behavior of glioblastomas together with increased angiogenesis." (PMID 28629170, 2017). "The most common and best-studied EGFR alteration in glioblastomas is the EGFR type III variant (EGFRvIII), a constitutively active genomic deletion variant lacking exons 2 to 7 of the EGFR gene, usually occurring in EGFR-amplified tumors." (PMID 29371993, 2017). "In glioblastoma, EGFR is overexpressed or mutated which causes truncation of EGFR (EGFRvIII) and its constitutive activation." (PMID 28338617, 2017). "High serum EGFR and ErbB2 levels were associated with risk of developing glioblastoma (P = 0.008; OR = 1.58, 95 % CI = 1.13–2.22 and P = 0.017, OR = 1.63, 95 % CI = 1.09–2.44, respectively)." (PMID 26906551, 2016). "In glioblastoma, the EGFRwt overexpression is frequently associated with a mutated EGFR, labeled EGFRvIII, resulting from a rearrangement of the EGFR gene." (PMID 27104520, 2016). "EGFR amplification and TERTp mutation were only detected in 3.7% and 8.4% in young adult glioblastomas, respectively." (PMID 26452024, 2016). "All glioblastoma cell lines showed similar trends in response to all combinations, while EGFR variants were in some instances more resistant than parental." (PMID 27805565, 2016). "EGFR gene mutations are in the majority of glioblastomas accompanied by regional DNA amplification, leading to a higher number of copies of the mutated allele." (PMID 26906551, 2016). "EGFRvIII is a frequently occurring mutation in primary glioblastoma and renders EGFR constitutively phosphorylated and activated, resulting in fast growth and proliferation of tumor cells." (PMID 27581736, 2016). "EGFR alteration, including overexpression or gene amplification, is the most frequent form of genetic mutation, occurred in 40-50% of glioblastomas." (PMID 26967052, 2016). "One phenotypic trait of glioblastoma is the mutation and amplification of the epidermal growth factor receptor (EGFR) gene." (PMID 26906551, 2016).
glioblastoma (continued). "Several clinical and histopathological studies reported that amplification and overexpression of EGFR was associated with a shorter interval to relapse and poor survival in glioblastoma patients, low-grade glioma patients and anaplastic astrocytoma patients." (PMID 27437777, 2016). "Further, oncogenic EGFR mutations in glioblastoma are associated with apoptotic resistance via increased Bcl-xL expression." (PMID 27805565, 2016). "This was consistent with a previous report indicating that EGFR vIII overexpression in glioblastoma cells caused increased levels of ROS, DNA strand breaks accumulation, and genome instability." (PMID 27563812, 2016). "By dichotomizing pre-diagnostic serum protein concentration according to the median of the control population, we found that both high levels of EGFR and ErbB2 were associated with glioblastoma risk." (PMID 26906551, 2016). "Glioblastomas display EGFR overexpression in greater than 80% of samples and more than 50% display additional expression of EGFR deletion variant EGFRvIII." (PMID 27153091, 2016). "Our results parallel the situation seen in glioblastoma multiforme in which overexpression or amplification of EGFR and its variant, EGFRvIII, is commonly associated with PTEN deletion or mutation." (PMID 27484095, 2016). "Amongst the described examples the point mutation in gene coding epidermal growth factor receptor (EGFRvIII) was found in EVs isolated from glioblastoma patients." (PMID 27199663, 2016). "The Cancer Genome Atlas (TCGA) consortium identified six somatic mutations in glioblastomas that affect EGFR protein structure, ranging from extracellular domain point mutations and deletions to deletions in the cytoplasmic tail of the receptor." (PMID 26906551, 2016). "To model this cancer type, we used the U87 glioblastoma cell line expressing either vector, wild-type EGFR (wtEGFR), EGFRΔIII, or EGFR with the R108K mutation (R108K)." (PMID 26136341, 2015). "The epidermal growth factor receptor is the predominant receptor tyrosine kinase targeted by both amplification and mutation in adult glioblastomas." (PMID 26248280, 2015). "Further, in glioblastomas with activating mutation in EGFR, NF-κB is activated through mTORC2 in an SGK1-dependent manner that does not require Akt or mTORC1, underlying the Akt-independence of this pathway." (PMID 26219339, 2015). "EGFRvIII, the most frequently occurring EGFR mutation in primary glioblastoma, encodes a protein product that constitutively signals regardless of EGF ligand." (PMID 25992628, 2015). "EGFR is an activator of PLCγ1 and EGFR gene amplification is one of the most frequent alterations occurring in glioblastoma and associated with profuse tumor cell invasion." (PMID 26098895, 2015). "A constitutively active mutation of EGFR (EGFRvIII) is found in 20–30% of glioblastomas and typically occurs in the presence of over-expression (amplification) of the wild type transcript." (PMID 25785247, 2015). "Our long range PCR analysis of HNSCC and glioblastoma samples revealed a large number of breakpoints in intron 1 of EGFR that resulted in loss of exons 2–7 at the genomic level." (PMID 25658924, 2015). "We found that PEDF is secreted from glioblastoma expressing EGFRvIII, a frequently occurring mutation in primary glioblastoma that yields a permanently activated epidermal growth factor receptor." (PMID 25992628, 2015). "For example, analysis of epidermal growth factor receptor (EGFR) mutations and amplifications in glioblastoma patients revealed a transient extrachromosomal amplification of a specific EGFR isoform." (PMID 25995187, 2015). "The small cell variant of glioblastoma has morphological similarities to anaplastic oligodendroglioma but carries EGFR amplification in 70 % of cases." (PMID 25943885, 2015).
glioblastoma (continued). "It happens in glioblastoma through upregulation or a gain-of-function mutation of receptor tyrosine kinases (RTKs), such as epidermal growth factor receptor (EGFR), platelet-derived growth factor receptor (PDGFR), and fibroblast growth factor receptor (FGFR)." (PMID 25913706, 2015). "The elimination of DMs carrying EGFR-vIII from glioblastoma cells can be caused by specific tyrosine kinase inhibitors." (PMID 26075403, 2015). "Glioblastoma is a highly aggressive astrocytic tumor of the brain in which the gene encoding the EGFR is frequently amplified, driving tumorigenicity." (PMID 26283964, 2015). "Recently, mitochondrial EGFR and the EGFR variant, EGFRviii, are reported to be constitutively active and present in the mitochondria of glioblastoma cells." (PMID 26497368, 2015). "Many glioblastomas, the most common type of brain tumor, are characterized by the amplification in DMs of EGFR-vIII, a gene encoding a constitutively active form of EGFR." (PMID 26075403, 2015). "In glioblastoma multiforme, it is well established that overexpression and mutation of the EGFR contributes to aggressiveness through increased proliferation, survival, and migration." (PMID 25052069, 2014). "Monochloro-GM3, but not GM3 or dichloro-GM3, showed a significant inhibitory effect on ΔEGFR, a splicing variant of EGFR that lacks exons 2–7 and is often found in human glioblastomas." (PMID 24944646, 2014). "EGFRvIII is the most prevalent of several epidermal growth factor receptor (EGFR) mutations found in human glioma and is expressed in 20–25 % of glioblastoma (GBM) cases." (PMID 24816916, 2014). "While EGFR is frequently mutated or amplified during glioblastoma pathogenesis, clinical experiences with EGFR inhibitors have been disappointing." (PMID 24658464, 2014). "PTEN mutation and EGFR amplification are key prognostic factors in patients with anaplastic astrocytoma and in older patients with glioblastoma multiforme." (PMID 24650032, 2014). "We have designed a Phase I clinical study of CAR T cells transduced with humanized scFv directed to EGFR variant III in patients with glioblastoma." (PMID 25746013, 2014). "Instead, we have discovered that PHD3 loss sustains proliferative signalling in glioblastomas through the upregulation of EGFR phosphorylation." (PMID 25420773, 2014). "It is well known up to 65% of so-called primary glioblastomas show epidermal growth factor receptor (7p12) amplification, overexpression, and/or mutations of this pathway." (PMID 24716189, 2014). "In this study we provide what is to our knowledge the first report of association between microRNA-200c and EGFR amplification in glioblastomas." (PMID 25058589, 2014). "Induction of G-CIMP+ state by exogenous expression of a mutated isocitrate dehydrogenase 1, IDH1-R132H, suppressed EGFR and H-Ras protein expression as well as pERK accumulation in independent glioblastoma models." (PMID 25277177, 2014). "CAR-T cells were also able to control tumor growth in xenogeneic subcutaneous and orthotopic models of human EGFR variant III+ glioblastoma." (PMID 25746013, 2014). "About half of the glioblastomas exhibit EGFR anomalies including amplification and mutation of the EGFR gene and/or increased EGFR protein expression." (PMID 24736727, 2014). "Many of the genes identified through this meta-analysis have in fact been implicated in development of astrocytoma including EGFR (amplification occurs in ∼40% of primary glioblastomas, HIF-1α, MYC, WNT5A, and IDH3A." (PMID 23737970, 2013). "We also identified one patient with an EGFR-C326S mutation, a position previously seen mutated in glioblastoma, as well as one patient with a NRAS-Q61K mutation, common in melanoma but never seen in gliomas." (PMID 23441165, 2013).
glioblastoma (continued). "We applied our approach to integrate epigenomic, phosphoproteomic and transcriptome changes induced by the variant III mutation of the epidermal growth factor receptor (EGFRvIII) in a cell line model of glioblastoma multiforme (GBM)." (PMID 23408876, 2013). "There is a specific type of EGFR mutation, called de2-7EGFR or EGFRvIII, whose expression is often found in glioma or glioblastoma multiforme (GBM)." (PMID 23702846, 2013). "Our study explored the use of [125I]PYK as a potential probe for detection of EGFR mutations in xenografts of U87 glioblastoma cells in mice to predict treatment with gefitinib treatment." (PMID 27408849, 2013). "Glioblastomas, the most common primary brain tumor, harbor mutations in receptor tyrosine kinases (RTKs), such as EGFR, and components of the Pi-3 kinase (PI3K) signaling pathway." (PMID 23459592, 2013). "Other glioblastoma mutations, including mutations in the EGFR, PIK3CA and PIK3R1 genes, also activate this pathway." (PMID 23907540, 2013). "In patients with glioblastoma multiforme, a mutation affecting the EGFR receptor predicts sensitivity to EGFR inhibitors only when the tumor suppressor PTEN is also intact." (PMID 23577104, 2013). "The low frequency of IDH mutations in the gliomas with EGFR amplification most likely accounts for the low IDH mutations rate in primary glioblastomas compared with secondary glioblastomas." (PMID 23894344, 2013). "In approximately 14% of EGFR-expressing glioblastomas there is a mutation in the EGFRvIII gene, which is characterized by a lack of an extracellular domain and constitutive phosphorylation." (PMID 24381541, 2013). "Glioblastoma multiforme cells that express a constitutively active variant of the epidermal growth factor receptor (EGFR) underwent decreased adhesion, spreading and invasion when transfected with a siRNA targeting MARCKS." (PMID 23840497, 2013). "The receptor tyrosine kinase pathway in glioblastoma is reported to be over activated by events like amplification and activating mutations of EGFR." (PMID 23690991, 2013). "Glioblastomas harboring EGFR gene amplification frequently contain a genetic variant, EGFRvIII, which encodes a mutant receptor with an altered extracellular domain that renders it constitutively active." (PMID 22159595, 2012). "The EGFR gene is highly variable, and both EGFR gene amplification and mutation have been frequently observed in glioblastoma tumors." (PMID 22662167, 2012). "EGFR gene amplification concerned only glioblastomas and was associated with the presence of EGFRvIII and high levels of EGFRv2, -v3 and -v4 transcripts." (PMID 22159595, 2012). "Regarding the relationships with the prognosis in our series, the histological type (astrocytoma and glioblastoma), a strong staining with Int-Ab and the presence of EGFR amplification and of mutant vIII were associated with shorter PFS and OS times." (PMID 22159595, 2012). "Although high levels of EGFR most likely underlie some malignant adaptations in glioblastomas, only small subsets of patients have responded to therapies targeted to EGFR in clinical trials." (PMID 22691727, 2012). "It has been reported that synthetic amplification of EGFR in heterozygous PTEN knockout causes mice to develop invasive brain tumors that closely resemble human glioblastomas." (PMID 22479427, 2012). "A pejorative outcome was associated with: histology (glioblastomas), EGFR amplification, strong Int-Ab labeling and high levels of variant mRNAs." (PMID 22159595, 2012). "While previous literature has advocated the independent prognostic significance of PTEN loss in glioblastoma, other studies have demonstrated the importance of EGFR amplification as well as other methods of Akt pathway activation in tumorigenesis." (PMID 22479427, 2012). "Amplification of EGFR or one of its variants, EGFRvIII, whose encoded protein is constitutively active, is well-known to occur in primary glioblastomas." (PMID 22691727, 2012).